RRN3P2 (RRN3 pseudogene 2)
Synonyms: RUNDC2C; SNX29P2
Gene: Long non-coding RNA gene on chromosome 16 (29,074,796 to 29,403,423, forward strand). Ensembl gene ENSG00000103472.
Diseases named in the same sentence as RRN3P2 in open-access papers:
RRN3P2 is named in the same sentence as 3 diseases in open-access papers, as found by Europe PMC text mining. Sharing a sentence is not in itself a finding about the gene and the disease. The quoted sentences say what the papers report.
lymph node metastasis (1 paper, 2020). "In addition, patients with lymph node metastasis had significantly higher expressions of PGM5P2, HERC2P4 and RRN3P2 but lower expressions of HLA-H and RPL13AP20 than those without lymph node metastasis." (PMID 33378744, 2020).
tumor (2 papers, 2020 to 2022). "RRN3P2, AL121772.1, AC245041.2, and AC147067.2 were revealed to be differentially expressed between normal tissues and tumor tissues." (PMID 35198013, 2022). "Interestingly, we observed that only RRN3P2, AL121772.1, AC245041.2, and AC147067.2 were differentially expressed between normal tissues and tumor tissues." (PMID 35198013, 2022).
RRN3P2 also shares sentences with these, for which no sentence is quoted: breast carcinoma (1 paper).